SYCE2 (synaptonemal complex central element protein 2)
Description:
Major component of the transverse central element of synaptonemal complexes (SCS), formed between homologous chromosomes during meiotic prophase. Requires SYCP1 in order to be incorporated into the central element. May have a role in the synaptonemal complex assembly, stabilization and recombination (By similarity).
Synonyms: CESC1
Tractability: PROTAC: ubiquitination databases record sites on it.
Gene: Protein-coding gene on chromosome 19 (12,898,786 to 12,919,306, reverse strand). Ensembl gene ENSG00000161860.
Subcellular location: Nucleus; Chromosome
Subcellular location (Human Protein Atlas): Nucleoplasm
Pathways (Reactome):
Reproduction: Meiotic synapsis
Gene Ontology:
Molecular function: protein binding
Biological process: homologous chromosome pairing at meiosis; homologous recombination; reciprocal meiotic recombination; synaptonemal complex assembly
Cellular component: nucleoplasm; central element; chromosome; condensed nuclear chromosome; nucleus; synaptonemal complex
Genetic constraint (gnomAD): Loss-of-function variants: 5 observed, 30.17 expected, observed/expected ratio (o/e) 0.17, 90% interval 0.086 to 0.35. The upper end of that interval is the gene's LOEUF score, 0.35, which puts it in group 1 of 6, group 1 being the genes least tolerant of losing a copy. Missense variants: 207 observed, 278.24 expected, observed/expected ratio (o/e) 0.74, 90% interval 0.66 to 0.83. Synonymous variants: 85 observed, 106.36 expected, observed/expected ratio (o/e) 0.8, 90% interval 0.67 to 0.96.
Homologues: Orthologues: chimpanzee SYCE2 (99% identical), dog SYCE2 (67% identical), mouse Syce2 (55% identical), pig SYCE2 (54% identical), tropical clawed frog syce2 (31% identical).
Diseases named in the same sentence as SYCE2 in open-access papers:
SYCE2 is named in the same sentence as 9 diseases in open-access papers, as found by Europe PMC text mining. Sharing a sentence is not in itself a finding about the gene and the disease. The quoted sentences say what the papers report.
gastric cancer (2 papers, 2018 to 2024). A primary or metastatic malignant neoplasm involving the stomach. "Although SYCE2 expression was detected in kidney and stomach cancers, as well as in lymphoma samples, no expression was detected in normal tissues from the same patients." (PMID 30456351, 2018).
Infertility (2 papers, 2011 to 2025). "In mice, mutations in Syce2 and Sycp1 lead to infertility due to a prophase I checkpoint that removes defective spermatocytes and oocytes." (PMID 40911633, 2025). "Detailed analyses of Syce2 and Tex12 knockout mice showed that loss of each of these two genes causes infertility in both sexes." (PMID 21637789, 2011).
cancer (3 papers, 2018 to 2022). A tumor composed of atypical neoplastic, often pleomorphic cells that invade other tissues. "Our findings shed light on a hitherto unappreciated function of SYCE2 in somatic cells with potential relevance for cancer." (PMID 30456351, 2018). "We show here that SYCE2 is expressed at varying elevated levels in somatic cancer cells in a demethylation-dependent manner and at very low levels in normal cells." (PMID 30456351, 2018). "We first examined SYCE2 expression in somatic cells by quantitative real-time RT–PCR analysis using human cancer cell lines from various tissues in addition to normal cell lines and normal human testis." (PMID 30456351, 2018). "Thus, to understand TEX12’s centrosome function in meiosis and cancer, alongside other potential SYCE2-independent cellular roles, we sought to elucidate the structure of the TEX12 dimer." (PMID 36071143, 2022). "The dissociation of HP1α from H3K9me3 by SYCE2 shown in our study might be one of the mechanisms for the increased steady-state ATM activity in cancer." (PMID 30456351, 2018). "Moreover, induction of SYCE2 expression was observed in the DLD1 and HT1080 cancer cell lines after treatment with the demethylating agent 5-azacytidine, indicating that SYCE2 expression is regulated by a demethylation-dependent process, as has been described for some cancer-testis antigens." (PMID 30456351, 2018). "Thus, the SYCE2 expression levels, which vary among cancers, may define the background ATM-mediated DNA repair capacity of each cancer." (PMID 30456351, 2018). "Our findings provide the structural basis for SYCE2-independent roles of TEX12, including the possible regulation of SC assembly, and its known functions in meiotic centrosomes and cancer." (PMID 36071143, 2022). "Although SYCE2 expression was not expected in nonmeiotic cells, aberrant expression of SYCE2 was detected in various cancer cell lines and at varying low levels in normal cell lines." (PMID 30456351, 2018). "The changes in the HP1α localization were observed in both non-cancerous cells expressing low levels of SYCE2 and cancer cells expressing rather high levels of SYCE2." (PMID 30456351, 2018). "As SYCE2 is expressed at varying elevated levels in cancer cells as opposed to normal cells, SYCE2 might be a prime candidate target for cancer selective therapy." (PMID 30456351, 2018).
tumor (2 papers, 2018 to 2020). "We further examined the expression of SYCE2 in primary tumors by RT–PCR analysis using commercially available samples and found SYCE2 expression in the cervix, ovary, thyroid, and uterus tumor samples, and high expression in the normal testis." (PMID 30456351, 2018).
SYCE2 also shares sentences with these, for which no sentence is quoted: lung adenocarcinoma (1 paper); lymphoma (1); neuroblastoma (1); stomach cancers (1); uterus (1).